EXOC1L (exocyst complex component 1 like)
Gene: Protein-coding gene on chromosome 4 (55,819,790 to 55,837,489, forward strand). Ensembl gene ENSG00000250821.
Homologues: Orthologues: chimpanzee EXOC1L (99% identical), dog EXOC1L (99% identical), macaque EXOC1L (98% identical), pig EXOC1L (98% identical), guinea pig EXOC1L (98% identical), rabbit EXOC1L (97% identical), rat Exoc1l (91% identical), mouse Exoc1l (90% identical), tropical clawed frog exoc1l (66% identical), zebrafish exoc1l (48% identical), Caenorhabditis elegans sec-3 (20% identical), Drosophila melanogaster Sec3 (20% identical). Paralogues in human: EXOC1 (33% identical), STXBP6 (20% identical).